KRAS (KRas proto-oncogene, GTPase)
Diseases named in the same sentence as KRAS in open-access papers (continued):
Sharing a sentence is not in itself a finding about the gene and the disease.
pancreatitis (61 papers, 2012 to 2025). Inflammation of the pancreas. "The initiation of PDAC is generally attributed to either pancreatitis or oncogenic KRAS mutation (mu-KRAS)." (PMID 40707469, 2025). "During pancreatitis, oncogenic kirsten rat sarcoma viral oncogene homolog (KRAS) mutations accelerate tumor progression." (PMID 41169375, 2025). "The five most highly ranked features in the XGBoost model were KRAS gene mutation status, age, alcohol consumption status, pancreatitis status, and hyperlipidaemia status." (PMID 39640479, 2024). "The study identified KRAS gene mutation, age, alcohol consumption status, pancreatitis status, and hyperlipidaemia status as the five most common potential risk factors." (PMID 39640479, 2024). "Increased presence of inflammatory macrophages can be found in response to a KRAS mutation in acinar cells or in response to experimentally-induced pancreatitis." (PMID 38576613, 2024). "When pancreatitis occurs, inflammatory microenvironment accelerate tumor development with the activation of KRAS mutations." (PMID 38287020, 2024). "A pathogenic variation in GNAS is suggestive for an IPMN and the interpretation of a pathogenic variant in KRAS remains somewhat challenging since this can be seen in in IPMNs, malignancies but also in pancreatitis." (PMID 36696439, 2023). "There is a synergic relationship between KRAS activation and inflammation, as KRAS expression is itself highly proinflammatory, and the duration of pancreatitis is associated with the predisposition to KRAS mutations." (PMID 37174095, 2023). "Secondly, in case of LGD, the identification of a sole KRAS pathogenic variant can indicate a pancreatitis, IPMN or malignancy." (PMID 36696439, 2023). "The duration of pancreatitis appears to correlate positively with a stepwise increase in the degree of KRAS mutation correlating with the grade of dysplasia of pancreatic intraepithelial neoplasia (PanIN) lesions and eventually leading to PDAC development." (PMID 34359684, 2021). "Our findings show that KRAS mutation testing demonstrates a high degree of specificity once patients with pancreatitis or benign pancreatic tumours are excluded." (PMID 32825312, 2020). "From this perspective, our antibody enabled us to emphasize an increase in KRAS prenylation rates in pancreas bearing KrasG12D mutation following the induction of pancreatitis." (PMID 32887255, 2020). "Expression of the VMP1 protein, and its triggered autophagy, is therefore induced and maintained by mutation of the KRAS oncogene, which is strongly reinforced during the course of pancreatitis." (PMID 27833900, 2016). "Finally, we analysed the diagnostic accuracy of KRAS mutation testing in a population of patients with pancreatitis." (PMID 32825312, 2020). "NR5A2 is an important regulator of exocrine function in the adult pancreas where it maintains homeostasis and promotes regeneration of acinar cells after inflammation caused by chemically induced pancreatitis, and protects the pancreas from KRAS driven pre-neoplastic changes." (PMID 27579533, 2016). "Based on our previous reports that loss of PEDF accelerates cerulein-induced pancreatitis and fibrosis and mutant KRAS-induced pancreatic tumorigenesis, we hypothesized that PEDF may have tumor suppressor-like qualities." (PMID 27058416, 2016). "Loss of RalGAP impacts secretion, cell polarity, and primary cilium formation, results in pancreatitis and neoplasia development in the pancreas, and promotes mutant KRas-driven tumorigenesis." (PMID 40490362, 2025).
pancreatitis (continued). "Inducing pancreatitis in mice produced ECM architectures conducive to invasion, effectively “priming” the stroma for early dissemination, aligning with observations that pancreatitis increases early dissemination in KRAS-mutant models." (PMID 41394398, 2025). "Pancreatitis is a risk factor for the development of PDAC in humans and cooperates with oncogenic KRas mutations to induce PDAC formation in mice." (PMID 38902237, 2024). "If IL-1Ra is induced during pancreatitis, which is consistent with the early induction of IL-1Ra in preinvasive lesions, it can utilize its unique functions, e.g., protecting KRAS-induced arrest and immune surveillance, to precondition the pancreas." (PMID 37563620, 2023). "Recent work leveraging scRNA-seq data from the mouse pancreas undergoing chemically induced pancreatitis reveals that mutant KRAS hijacks normal regenerative cell state transitions for tumor promotion." (PMID 37387147, 2023). "Other sets of co-upregulated genes included ‘KRAS signaling up’ and ‘inflammatory response’, which lead to pancreatitis, pancreatic intraepithelial neoplasia (PanIN) and eventually PDAC34." (PMID 35995947, 2022). "Toll-like receptors’ activation can fuel pancreatitis and synergise with KRAS to accelerate pancreatic carcinogenesis in mice." (PMID 34359684, 2021). "Here, we delineate the role of Euchromatic Histone-lysine N-Methyltransferase 2 (EHMT2), the enzyme that generates H3K9me, as a downstream effector of oncogenic KRAS during PDAC initiation and pancreatitis-associated promotion." (PMID 34249932, 2021). "KRAS mutation was detected in PDAC patients, but also in a significant proportion of patients with pancreatitis or benign pancreatic tumours across multiple studies using a range of biochemical methodologies." (PMID 32825312, 2020). "If expression of oncogenic KRAS was induced after pancreatitis induction, this would only induce PDAC in mice if residual inflammation was still present." (PMID 30340359, 2018). "Pancreatitis is an inflammatory disease that both facilitates and accelerates the transformation of pancreatic cells upon activation of the KRAS oncogene." (PMID 27833900, 2016). "Pancreatitis, an inflammatory disease of the pancreas, enables and accelerates the transformation of pancreatic cells when the KRAS oncogene is activated." (PMID 27833900, 2016). "Among the upstream mediators activated in the Ptf1a cKO model are TNF-α and NFkB, both of which promote ADM and inflammation in pancreatitis and amplify KRAS activity in pancreatic tumorigenesis." (PMID 26151762, 2015). "Similarly, pancreatitis-induced ADM cooperates with oncogenic KRAS to drive pancreatic cancer progression by activating YAP1/TAZ, which in turn upregulate JAK-STAT3 signaling, promoting PDAC development." (PMID 40707469, 2025). "At least one KRAS mutation was detected in 6/18 (33.3%) paired plasma-derived cfDNA samples (1 patients with PDAC, 1 patient with IPMN, 1 patient with pancreatitis, and 3 controls), with mean FA values of 5.1% (+16.1) and 0.2% (+0.5) in the cases and controls, respectively." (PMID 39126005, 2024). "A KRAS mutation at codon 12 was detected by ddPCR in DF-derived cfDNA samples from 15/18 (83.3%) subjects (3 PDAC patients, 1 CCA patient, 2 IPMN patients, 2 pancreatitis patients, and 7 controls)." (PMID 39126005, 2024). "Nearly all PDA harbor active mutations in the KRAS gene, but KRAS mutations alone are insufficient for the development of PDA without the assistance of pancreatitis-induced inflammation." (PMID 37563620, 2023). "Consequently, the current study was designed to begin filling this gap in knowledge by studying how the pancreatitis-associated protein VMP1, a key regulator of autophagy, cooperates with oncogenic KRAS to give rise to PanINs." (PMID 27415425, 2016).
pancreatitis (continued). "The most likely hypothesis is that autophagy induced by pancreatitis, and mediated by overexpression of VMP1, provides the energy required of cells harboring an activating mutation in the KRAS oncogene, therefore allowing their transformation." (PMID 27833900, 2016). "All C2 cases showed no mutations in the KRAS gene and they were benign cysts (3 cases) or pancreatitis (one case) on follow-up." (PMID 24504548, 2014). "KRAS can induce PDA development, provided that there is a pancreatitis." (PMID 37591827, 2023). "Overall, these data suggest that during the process of pancreatitis-enhanced carcinogenesis by KrasG12D, EHMT2 influences immunomodulatory processes, while reducing EMT, TNF-α signaling via NFκB, and KRAS signaling, which have well-documented effects on growth promotion." (PMID 34249932, 2021). "We detected multiple KRAS-G12D mutant protein islands in Sirt2−/− but not in wild-type pancreas 7 days after caerulein-induced pancreatitis." (PMID 30405152, 2018). "For example, cerulein induces pancreatitis, but not PDAC, in mice without KRAS mutation, and induces pancreatitis, PanIN, and PDAC in mice with genetic KRAS mutations." (PMID 30338223, 2018). "Furthermore, previous studies indicated that KRAS and MAPK are required for the development of ADM and PanIN in mice, and MAPK was found to be upregulated in pancreatitis." (PMID 25905463, 2015). "Importantly, the ectopic expression of ST6GAL1 in acinar cells induces a pronounced upregulation in a ductal gene network (in the absence of either pancreatitis or the KRAS oncogene), as evidenced by RNA-Seq results and staining of SC tissues for SOX9, KRT8, and KRT19." (PMID 37643018, 2023).
lung squamous cell carcinoma (60 papers, 2011 to 2026). "A previous study stated that KRAS variant is quite frequent in adenocarcinoma and squamous cell lung carcinoma." (PMID 38245692, 2024). "In NSCLC, KRAS mutations occur in 30% of adenocarcinoma and less frequently (about 7%) in squamous-cell lung carcinoma." (PMID 35004317, 2021). "Distribution of codon 12/13 KRAS mutations in advanced non-squamous cell lung carcinoma from this study compared with the frequency distribution in the Cosmic database." (PMID 23922984, 2013). "In Caucasian patients with non-squamous cell lung carcinoma, the KRAS mutation is most common (20–30% of cases), followed in frequency by mutations in the EGFR gene (10–20% of cases)." (PMID 23922984, 2013). "KRAS mutation frequency in squamous cell lung carcinoma in smokers is 2.7%." (PMID 33549031, 2021). "Initial studies reported that although in a much lower percentage, KRAS mutations might be present not only in LADC but also in squamous cell lung cancer." (PMID 32548736, 2020). "The majority (6/7) of all cases with KRAS mutations were squamous cell lung cancers." (PMID 21414214, 2011). "Tumor heterogeneity, especially in the metastatic phase, is influenced by various factors including histological subtypes (such as adenocarcinoma and squamous cell lung cancer) and genetic mutations (such as those in EGFR, BRAF, KRAS, and ALK translocations)." (PMID 39518079, 2024). "In 134 lung squamous cell carcinoma tissue samples, there were 7 (5.2%) EGFR mutations, 6 (4.5%) KRAS mutations, 12 (9.0%) PIK3CA mutations, 1 (0.7%) BRAF mutations and 1 (0.7%) MET amplifications." (PMID 31749831, 2019). "In 96 lung squamous cell carcinoma blood samples, there were 8 (8.3%) EGFR mutations, 7 (7.3%) KRAS mutations, 6 (6.3%) PIK3CA mutations and 1 (1.0%) BRAF mutations." (PMID 31749831, 2019). "The Combination of PKCι-PAK1 inhibitors was highly synergistic in EGFR and KRAS mutant adenocarcinoma and squamous cell carcinoma of the lung, in both in vitro and in vivo mice models." (PMID 31660987, 2019). "A total of 139 patients undergoing treatment for na?ve lung squamous cell carcinomas with tumor tissue samples available for testing were recruited.EGFR and KRAS mutation statuses of the tumor samples were detected using a mutant enriched liquid chip." (PMID 26483334, 2015). "We found that patients with KRAS-variant squamous cell lung cancer had significantly worse OS than non-variant squamous patients (HR = 1.76, CI = 1.07–2.90, log-rank test P = 0.0307 stratified by as-treated radiation dose level and cetuximab)." (PMID 37728512, 2023). "The cell lines we studied all express wild-type KRAS, suggesting against this possibility, but we speculate that a similar mechanism driven by a different oncogene may function in squamous cell lung cancer cells." (PMID 36697489, 2023). "Nevertheless, more recent results suggest that, in most cases, KRAS mutations do not occur in pure squamous-cell lung carcinoma but in mixed histology of adenosquamous or neuroendocrine carcinomas." (PMID 35004317, 2021). "However, recent analysis using up-to-date differential diagnostic criteria suggests that KRAS mutations do not occur in pure pulmonary squamous cell lung carcinomas, and in case detected, it is confined to LADC components in squamous cancer." (PMID 32548736, 2020).
lung squamous cell carcinoma (continued). "In an effort to further elucidate the expression patterns of SHP2 in a clinical context, we conducted protein expression analysis in KRAS wild‐type and mutant tissues within LUAD and lung squamous cell carcinoma (LUSC) from the TCGA database." (PMID 39992860, 2025). "The EZH2 gene expression of lung squamous cell carcinoma was positively correlated with the gene expression of BRAF (r = 0.3662, p < 0.0001) and KRAS (r = 0.3567, p < 0.0001)." (PMID 37069494, 2023). "Notably, the ubiquitome analysis of the Clinical Proteomic Tumor Analysis Consortium (CPTAC) lung squamous cell carcinoma (LUSC) dataset revealed that lung tumor samples presented decreased levels of NRAS and KRAS ubiquitination at K128 in comparison to normal tissue." (PMID 38858602, 2024). "In Calu-3 (HER2-amplified, KRAS-wt, lung squamous cell carcinoma), dabrafenib-induced paradoxical ERK activation could not be abrogated by simultaneous MEK inhibition and pharmacological interactions between the two drugs were highly antagonistic (CI: 19.3)." (PMID 29986755, 2018). "However, no region was detected positive for lung squamous cell carcinoma (LSCC) markers P40 and CK5/6, indicating that KRAS mutant organoid transplantation can induce a phenotype resembling LUAD." (PMID 41208901, 2025).
sarcoma (57 papers, 2008 to 2026). A usually aggressive malignant neoplasm of the soft tissue or bone. "Kristen rat sarcoma (KRAS) mutations occur in up to 40% of CRCs and serve as both a prognostic and predictive biomarker." (PMID 37569406, 2023). "In the STS cohort, KRAS G12C mutations were identified angiosarcoma (n=2), sarcoma NOS (n=2), myxoid/round-cell liposarcoma (n=1), and undifferentiated pleomorphic sarcoma (n=1)." (PMID 36741731, 2022). "This new assay for the detection of KRAS mutation would have an important application for the diagnosis of other types of tumors, such as head and neck cancer and sarcoma." (PMID 33467412, 2021). "Only one previous study reported that different KRAS mutations in a case of primary ovarian mucinous adenocarcinoma with mural nodule of high grade sarcoma." (PMID 32290854, 2020). "The Kirsten rat sarcoma (KRAS) is said to be one of the most activated oncogenes with 17 to 25% of all human tumors harboring an activating KRAS mutation, resulting in gene activation with transforming ability of the mutant proteins." (PMID 31088372, 2019). "Current guidelines in Europe and the USA recommend that all mCRC patients receive Kirsten rat sarcoma (KRAS) testing prior to treatment with EGFR inhibitors since KRAS mutation status–wild type (WT) or mutant (MT)–predicts the response to anti-EFGR therapies." (PMID 30256829, 2018). "Responder patients had mutations around the rapidly accelerated fibrosarcoma (RAF)-rat sarcoma (RAS)-ERK pathway including KRAS/BRAF and MEK-related mutations that predicted the profiles to have stronger expression of PD-L1." (PMID 29486723, 2018). "Although KRAS is infrequently mutated in sarcomas, KRAS mutations occur in undifferentiated pleomorphic sarcomas as well as in rhabdomyosarcomas, which account for nearly half of pediatric soft tissue sarcomas." (PMID 29233960, 2017). "The tumor was right-sided, and Kirsten rat sarcoma (KRAS) mutated based on that." (PMID 37034492, 2023). "Kirsten rat sarcoma (KRAS) and mutant KRASG12D have been implicated in human cancers, but it remains unclear whether their activation requires ubiquitination." (PMID 38124228, 2023). "Low KRAS expression in the mesenchyme may explain why KRAS is weakly expressed in sarcomas and why KRAS mutations are rare in this type of cancer." (PMID 36238685, 2022). "KRAS mutations were extremely rare in a variety of sarcoma subtypes." (PMID 35359599, 2022). "In addition, KRAS mutations are also common in head and neck cancer and sarcoma." (PMID 33467412, 2021). "Using a pooled genetic screen based on The Cancer Genome Atlas (TCGA), the researchers identified key genes, in particular YAP1 and wild-type KRAS, as critical drivers of sarcoma development." (PMID 41123840, 2025). "While NTRK-Mono formed a very distinct group, NTRK-Pleo sarcomas clustered in a rather scattered fashion adjacent to KRAS/sgTrp53 and sgTrp53 tumors." (PMID 40523919, 2025). "The use of vitamin C (VC) in high doses demonstrates a potent tumor suppressive effect by mediating a glucose-dependent oxidative stress in Kirsten rat sarcoma (KRAS) mutant cancer cells." (PMID 38473779, 2024). "Within the available NGS test panel, one patient with NTRK+ sarcoma also presented an EGFR L858R mutation, and one patient with NTRK+ NSCLC presented a KRAS G12 mutation." (PMID 35939431, 2022). "In recent years, even for Kirsten rat sarcoma (KRAS) gene alterations, used to considered “un–targetable”, new TKIs have emerged." (PMID 36532038, 2022). "Intracellular asparagine was depleted in KRAS-driven mouse sarcoma cells by abrogating asparagine synthesis via short hairpin RNA (shRNA)-mediated ASNS knockdown and culture in asparagine-free medium (A-N0)." (PMID 33499165, 2021).